SGMS2 (sphingomyelin synthase 2)
Diseases named in the same sentence as SGMS2 in open-access papers (continued):
Sharing a sentence is not in itself a finding about the gene and the disease.
glaucoma (2 papers, 2023 to 2025). Increased pressure in the eyeball due to obstruction of the outflow of aqueous humor. "Interestingly, the association of glaucoma with SGMS2 was further strengthened when Collantes and coworkers described a Filipino family harboring the SGMS2 p.Arg50* mutation, with characteristic skull lesions and juvenile onset open angle glaucoma." (PMID 37886644, 2023). "Less typical presentations of SGMS2-related skeletal disorders include myopia, glaucoma, and muscle function deficits." (PMID 40978119, 2025).
lymphoma (2 papers, 2021 to 2023). A malignant (clonal) proliferation of B- lymphocytes or T- lymphocytes which involves the lymph nodes, bone marrow and/or extranodal sites. "It is reported that lack of SGMS2 prolongs survival through Icam‐1 reduction in lymphoma." (PMID 36056909, 2023).
osteoarthritis (2 papers, 2019 to 2025). A noninflammatory degenerative joint disease occurring chiefly in older persons, characterized by degeneration of the articular cartilage, hypertrophy of bone at the margins and changes in the synovial membrane. "Moreover, recent studies have demonstrated expression of SGMS2 in primary chondrocytes isolated from patients with osteoarthritis, prompting the study of SGMS2 function also in this cell type." (PMID 30779713, 2019).
osteosarcoma (2 papers, 2015 to 2023). A usually aggressive malignant bone-forming mesenchymal neoplasm, predominantly affecting adolescents and young adults. "More interestingly, the expression of several of these genes, including CHST13, FKBP11, SGMS2, TRPS1, PRKX, SP7, and DNAJC1, were highly associated with osteosarcoma prognosis." (PMID 37457661, 2023). "Downregulation of miR-143 promotes osteosarcoma cell invasion through MMP-13 upregulation, and silencing of miR-133a reduces the malignancy of CD133high osteosarcoma-initiating cell population through restoring the expression of multiple target genes (SGMS2, UBA2, SNX30, and ANXA2)." (PMID 25912304, 2015).
pancreatic ductal adenocarcinoma (2 papers, 2022 to 2024). An infiltrating adenocarcinoma that arises from the epithelial cells of the pancreas. "Research has demonstrated a significant association between the expression of SGMS2 mRNA and the presence of tumor-associated macrophages (TAMs), as well as a negative impact on the prognosis of patients with pancreatic ductal adenocarcinoma (PDAC)." (PMID 38970097, 2024).
spondylometaphyseal dysplasia (2 papers, 2023 to 2025). Spondylometaphyseal dysplasias are a heterogeneous group of disorders associated with walking and growth disturbances that become evident during the second year of life. "Heterozygous SGMS2 missense variants c.185T>G (p.Ile62Ser) and c.191T>G (p.Met64Arg) result in a more severe phenotype with neonatal fractures, severe short stature, and spondylometaphyseal dysplasia." (PMID 40978119, 2025).
Alzheimer disease (1 paper, 2025). A progressive, neurodegenerative disease characterized by loss of function and death of nerve cells in several areas of the brain leading to loss of cognitive function such as memory and language. "Neurological symptoms are common in SGMS2-related skeletal disorders, particularly in severe cases, and include cranial nerve palsies, ataxia, reduced reflexes, and Alzheimer’s disease." (PMID 40978119, 2025).
Bruck syndrome (1 paper, 2025). Bruck syndrome is characterized by the association of osteogenesis imperfecta and congenital joint contractures. "Three patients were identified with mutations in the P3H1, LEPRE, CRTAP, SERPINF1, PLOD2 (Bruck syndrome), TGFB1, and SGMS2 genes (Calvarial Doughnut Lesions with Bone Fragility)." (PMID 39941180, 2025).
Cerebral ischemia (1 paper, 2024). Restriction of arterial blood supply to the brain associated with insufficient oxygenation to support the metabolic requirements of the tissue. "In addition, SGMS2 has been also described to attenuate inflammatory injury after cerebral ischemia–reperfusion in mice." (PMID 38785931, 2024).
congenital glaucoma (1 paper, 2025). "Interestingly, human patients with the pathogenic SGMS2 p.Arg50* variants have presented with eye defects such as congenital glaucoma." (PMID 41143154, 2025).
endothelial dysfunction (1 paper, 2021). In vascular diseases, endothelial dysfunction is a systemic pathological state of the endothelium (the inner lining of blood vessels) and can be broadly defined as an imbalance between vasodilating and vasoconstricting substances produced by (or acting on) the endothelium. "Our previous research also demonstrated that sphingomyelin synthase 2 (SMS2) can facilitate the accumulation of intracellular cholesterol, which contributes to the activation of ER stress and finally causes endothelial dysfunction." (PMID 34436503, 2021).
lupus (1 paper, 2024). "PKCδ's tolerance function is activated by sphingomyelin synthase 2 (SMS2), a lipid enzyme whose expression is generally reduced in B cells from lupus patients." (PMID 38927570, 2024).
melanoma (1 paper, 2019). A malignant, usually aggressive tumor composed of atypical, neoplastic melanocytes. "Moreover, melanoma expressed SGMS2 at rather low levels, while expressing UGCG at high levels." (PMID 31114500, 2019). "Accordingly, melanoma cells exhibited low SGMS1 and SGMS2 expression, while they expressed UGCG at higher levels." (PMID 31114500, 2019).
metastatic melanoma (1 paper, 2019). A melanoma that has spread from its primary site to another anatomic site. "In metastatic melanoma from the TCGA, the expression of UGCG was significantly higher than that of SGMS1 and SGMS2." (PMID 31114500, 2019). "Finally, the clinical outcome in metastatic melanoma patients exhibiting low (20th percentile, medium (between the 20th and 80th percentile), high (80th percentile) SGMS1, SGMS2, and UGCG expression was analyzed in the TCGA cohort." (PMID 31114500, 2019).
myocardial ischemia (1 paper, 2024). A disorder of cardiac function caused by insufficient blood flow to the muscle tissue of the heart. "Interestingly, two studies have reported miR-494-3p, which constitutes a miRNA–target transcript pair together SGMS2, to play a protective role in myocardial ischemia–reperfusion injury, repressing inflammation and apoptosis." (PMID 38785931, 2024).
pancreatic carcinoma (1 paper, 2022). "Sphingomyelin synthase 2 gene knockout (KO) mice and their controls were used to establish a PANC-02 orthotopic pancreatic cancer model, and immune cell infiltration in the tumor tissue was analyzed by immunohistochemistry (IHC)." (PMID 36324684, 2022).
tumor (18 papers, 2017 to 2025). "Conversely, Sgms2 expression was downregulated in hepatocytes, HSCs, ECs, immune cells, and macrophages of both pre-tumor and HCC groups but upregulated in cholangiocytes of the HCC group." (PMID 40057751, 2025). "In the SGMS2 knockout mouse model, the generation of M2‐type macrophages, tumor weight, and lung metastases lessened compared to the control group." (PMID 36056909, 2023). "Transwell and tumour invasion assays revealed that SGMS2 significantly enhanced the migration and invasion potential of both MCF-7 and MDA-MB-231 cells (P < 0.05)." (PMID 30770781, 2019). "We found that SGMS2 significantly promoted the proliferation of tumour cells in vivo in both MCF-7 and MDA-MB-231 cell lines (P < 0.05)." (PMID 30770781, 2019). "Compared with controls, more and bigger tumour nodules were found in the lungs of mice that received MDA-MB-231 cells overexpressing SGMS2 (P < 0.05)." (PMID 30770781, 2019). "KLF6 (p = 0.014) and SGMS2 (p = 0.031) were expressed more in tumor tissues compared to normal tissues, which suggested that KLF6 and SGMS2 might function as oncogenes in LUSC." (PMID 36056909, 2023). "This suggests that SGMS2 acts as a tumor suppressor gene in KIRC progression." (PMID 35846357, 2022). "To determine the protein levels of KLF6 and SGMS2, we obtained nine pairs of LUSC tumor and normal samples from patients for IHC staining." (PMID 36056909, 2023). "However, the role of SGMS2 in tumour metastasis and its underlying mechanism are still not clear." (PMID 30770781, 2019).
cancer (11 papers, 2018 to 2024). A tumor composed of atypical neoplastic, often pleomorphic cells that invade other tissues. "MGC26963, alternatively referred to as Sphingomyelin synthase 2 (SGMS2), is a genetic element that has been associated with multiple forms of cancer." (PMID 38970097, 2024). "SGMS2 promotes cancer cell invasion by enhancing TGF-β/smad signaling to initiate epithelial-mesenchymal transition." (PMID 36059802, 2022). "Whereas the gene expression level of SM synthase 2 (SGMS2), which catalyzes ceramide to SM, was equivalent between cancer and normal tissue." (PMID 30018456, 2018).
SGMS2 also shares sentences with these, for which no sentence is quoted: skeletal dysplasia (7 papers); infection (5); diabetes (2); type 2 diabetes (2); acute coronary syndrome (1); asthenospermia (1); Ataxia (1); atopic dermatitis (1); bone marrow failure syndrome (1); bovine tuberculosis (1); breast adenocarcinoma (1); cervical carcinoma (1); chlamydial infection (1); cholestasis (1); chronic obstructive pulmonary disease (1); colorectal cancer (1); Crohn disease (1); demyelination (1); depression (1); Duchenne muscular dystrophy (1); genetic disorders (1); Glucose intolerance (1); hepatoma (1); idiopathic osteoporosis (1); leukemia (1); lymph node metastasis (1); male infertility (1); metabolic syndrome (1); myocardial infarction (1); myopia (1).
A further 6 diseases each share a sentence with SGMS2 in 1 paper.